ERG (ETS transcription factor ERG)
Diseases named in the same sentence as ERG in open-access papers (continued):
Sharing a sentence is not in itself a finding about the gene and the disease.
prostate carcinoma (continued). "In preclinical studies a compound WP1130, inhibitor of deubiquinating enzyme USP9X was shown to restrain growth of prostate cancer in vitro and in vivo by promoting degradation of ERG protein." (PMID 25277175, 2014). "Leshem and colleagues (2011) found that the promoter region of IL1R2 possesses putative binding motifs for the TMPRSS2/ERG fusion gene, which is highly expressed in aggressive prostate cancer." (PMID 24359571, 2013). "Functional analyses performed thus far have not provided a comprehensive explanation for the selective pressure forcing ERG rearrangement in early stages of prostate cancer." (PMID 23390522, 2013). "We used the data to advance our current understanding of the biology of prostate cancer while focusing on the biology of ERG+ prostate cancer." (PMID 23390522, 2013). "ERG has a role in various leukemia and in Ewing sarcoma, and more recently it has been found as being overexpressed in some prostate cancer patients due to a genomic fusion with the androgen dependent promoter of the TMPRSS2 gene." (PMID 23915189, 2013). "Selective pressures favoring ERG rearrangement in prostate cancer presumably include enhanced migration, invasion, and dedifferentiation of prostate cancer cells, as well as exert an impact on energy balance, availability and consumption." (PMID 23390522, 2013). "Analogous to TMPRSS2/ERG in prostate cancer, the SLC1A2 fusion in gastric cancer is thought to be driven by strong expression of its 5′ partner, CD44." (PMID 23637631, 2013). "In summary, the present study was focused on population-independent transcriptional changes in prostate cancer and give first hints that ERG rearrangement in prostate cancer induces metabolic changes." (PMID 23390522, 2013). "Samples assigned to the ERG intermediate group were excluded from the analysis to ensure accurate comparison of ERG+ and ERG− prostate cancer samples." (PMID 23390522, 2013). "The question of how ERG accumulation influences the biology of prostate cancer cells in vitro and in vivo has gained a significant interest." (PMID 23555854, 2013). "Based on these initial results, we decided to use VCaP cells as an in vitro model to study the mechanistic relation between ERG and TDRD1 genes in ERG-rearranged prostate cancer." (PMID 23555854, 2013). "The rearrangements between the androgen receptor-regulated gene TMPRSS2 (21q22.3) and members of the ETS family member of transcription factor gene, most commonly ERG (21q22.2), are among the most common genetic alterations detected in prostate cancer." (PMID 24027643, 2013). "49% (76/155) of all genes found to be differentially regulated in ERG+ and ERG− prostate cancer in the meta-analysis were verified in the validation study." (PMID 23390522, 2013). "Gene fusions involving the androgen-regulated gene TMPRSS2 and ERG, a member of the ETS family of transcription factors, occur in about 50% of prostate cancers, especially in young patients, and result in strong ERG protein overexpression." (PMID 24261794, 2013). "They revealed that ERG promotes prostate cancer progression by working together with transcriptional corepressors including HDACs and EZH2." (PMID 23957008, 2013). "We are among the first to use a panel of TMPRSS2:ERG subtype markers for urine-based prostate cancer detection with high specificity and sensitivity." (PMID 24133629, 2013). "The early appearance and the high frequency of ERG rearrangements indicate the selective benefit of rearrangement-positive cells in prostate cancer." (PMID 23390522, 2013). "ERG rearrangement results in ERG over-expression and is observed in about 50% of all prostate cancer tissues." (PMID 23390522, 2013). "This database enabled assessment of the effect of p27 separately and in the two major molecular subgroups of prostate cancer, as defined by the ERG fusion status." (PMID 24179503, 2013).
prostate carcinoma (continued). "The comparative meta-analysis revealed 109 up-regulated and 58 down-regulated genes (fold-change >1.5; adjusted p-value <0.1; 36 genes were more than 2-fold regulated) in ERG+ as compared to ERG− prostate cancer." (PMID 23390522, 2013). "Strong MTC02 immunostaining was slightly more prevalent in ERG fusion positive prostate cancers, regardless if the ERG status was obtained by IHC or FISH analysis (p < 0.0001 each)." (PMID 24261794, 2013). "In mice, the introduction of constitutively active AKT kinase in Sca-1-enriched prostate epithelial cells resulted in tumor initiation and, in human cells, over-expression of AKT, ERG and AR in luminal cells generated prostate cancer." (PMID 24086346, 2013). "To gain new insights about the role of ERG-rearrangements in prostate cancer, we investigated the functions of differentially regulated genes in ERG+ prostate cancer cells." (PMID 23390522, 2013). "We performed two comparisons in the meta-analysis (cancer vs. benign prostate tissue and ERG+ vs. ERG− prostate cancer) so that the study would be of interest to a large scientific community." (PMID 23390522, 2013). "ERG gene rearrangements and ERG expression have been documented in roughly 50% of localized prostate and locally advanced castrate resistant prostate cancer compared to 12%–15% in watchful waiting or incidental cohorts." (PMID 24027643, 2013). "Combined with the detection of other critical genomic biomarkers for prostate cancer such as ERG, androgen receptor, and MYC, the evaluation of PTEN genomic status has proven to be invaluable for patient stratification and management." (PMID 24062990, 2013). "As NPY is overexpressed in ERG+ prostate cancer cells, these data provide first signs of the fact that ERG rearrangements in prostate cancer possibly modulate metabolic functions through expression of metabolic regulators like NPY." (PMID 23390522, 2013). "The large number of cases included in prostate cancer TMAs increasingly enables the selective analysis of relevant, molecularly defined subsets, such as ERG-positive prostate cancers." (PMID 24179503, 2013). "Accordingly, in mouse models of prostate cancer ERG was shown to cooperate with PI3K pathway to drive carcinogenesis." (PMID 23555854, 2013). "To identify transcriptional changes in prostate cancer, including tumors with ERG gene rearrangements, we performed a meta-analysis on published gene expression data followed by validations on mRNA and protein levels as well as first functional investigations." (PMID 23390522, 2013). "We focused on transcriptional changes in ERG rearrangement-positive (ERG+) prostate cancer, because these tumors constituted a less-characterized subgroup of prostate cancers." (PMID 23390522, 2013). "We expected the results of this investigation to yield a publicly accessible database for gene expression alterations in prostate cancer and provide new insights into the biology of ERG+ prostate cancers." (PMID 23390522, 2013). "One of the important questions brought up by this study concerns the consequences of TDRD1 accumulation in ERG-rearranged prostate cancer." (PMID 23555854, 2013). "So far, data on ERG rearrangement and prostate cancer progression are very inconsistent, reporting a positive, no or even a negative correlation." (PMID 23390522, 2013). "In summary, we found robust population-independent transcriptional changes in prostate cancer and first signs of ERG rearrangements inducing metabolic changes in cancer cells by activating major metabolic signaling molecules like NPY." (PMID 23390522, 2013). "Data of the entire panel across different individuals showed that prostate cancer patients with PTEN deletion also tended to exhibit abnormal results in TMPRSS2/ERG FISH." (PMID 24098661, 2013).
prostate carcinoma (continued). "The new observations of the ethnic differences of the ERG oncogene, the most common prostate cancer gene, are providing new insights into ERG based stratification of prostate cancers in the context of ethnically diverse patient populations." (PMID 23892597, 2013). "84% and 49% (fold-change>2 and >1.5, respectively) of all transcriptional changes between ERG+ and ERG− prostate cancer determined by meta-analysis were verified in the validation study." (PMID 23390522, 2013). "Our study indicates that metabolic changes possibly contribute to the selective pressure favoring ERG rearrangements in prostate cancer." (PMID 23390522, 2013). "Functional analyses performed thus far have been unable to fully explain the selective pressure forcing ERG rearrangement in early stages of prostate cancer." (PMID 23390522, 2013). "The most frequent genomic rearrangement in prostate cancer is fusion of the Ets transcription factor, Ets related gene (ERG), with the promoter of the highly-expressed transmembrane protease serine 2 (TMPRSS2) gene." (PMID 22860005, 2012). "The ERG gene has been observed to be one of the most commonly overexpressed proto-oncogenes in prostate cancer and present in approximately 72% of cases of prostate cancer." (PMID 22738151, 2012). "More than 50% of human prostate cancers overexpress ERG (v-ets avaian erythroblastosis virus E26 oncogene related gene)." (PMID 22325146, 2012). "A similar pattern was observed in prostate cancer: the complete exon-1 of TMPRSS2 was identified to fuse with ETV1 or ERG as one of the most recurrent rearrangements." (PMID 22496636, 2012). "AIM1, ERGIC1, and TPX2 were shown to be highly expressed especially in prostate cancer tissues, and high mRNA expression of ERGIC1 and TMED3 associated with AR and ERG oncogene expression." (PMID 22761906, 2012). "Previous study has shown that ETS (ETS1) transcription factor mediates adaptation to ER stress in melanoma cells, supporting the potential role of ERG in the regulation of ER function related genes in prostate cancer." (PMID 22761906, 2012). "First, the effect of salinomycin on the expression of key genes involved in prostate cancer, AR, ERG and MYC was studied." (PMID 22215106, 2012). "Taken together, these results suggest that the expression of the potential novel drug targets AIM1, ERGIC1, TMED3, and TPX2 is promoted by ERG oncogene and androgens in cultured prostate cancer cells." (PMID 22761906, 2012). "ERG induction and nuclear translocation resulted in the activation of the Wnt signaling pathway and promoted invasive capacity of prostate cancer cells." (PMID 22325146, 2012). "The TMPRSS2:ERG chromosomal rearrangement identified by Chinnayan’s pioneering studies in 2005 has become a molecular event of historic proportions in the prostate cancer field." (PMID 22641253, 2012). "Primary prostate epithelial cells demonstrated increased post transcriptional turnover of ERG compared to the TMPRSS2-ERG positive VCaP cell line, originally isolated from a prostate cancer metastasis." (PMID 22860005, 2012). "Further study into specific mechanisms of action of EZH2 have linked it with the gene fusion found in 50% of prostate cancers of TMPRSS2, an androgen-regulated gene, and the oncogenic ETS transcription factor ERG." (PMID 22641253, 2012). "We also applied EigFusion on independent prostate cancer data (455 samples) of known ERG fusion status." (PMID 22811706, 2012). "ERG mRNA is not expressed in healthy prostate tissues, but as a result of the TMPRSS2-ERG gene fusion early in carcinogenesis, a significant increase in ERG transcript levels can be detected in prostate cancers." (PMID 22761906, 2012). "Extensive investigation remains in order to understand the TMPRSS2:ERG gene fusion products role in prostate cancer progression, but it is clear that this molecular event is an early and important marker of prostate cancer." (PMID 22641253, 2012).
prostate carcinoma (continued). "To investigate the link between tERG and PIM1 in prostate cancer, we modulated ERG expression in the non malignant RWPE-1 prostate cell line." (PMID 22140532, 2011). "Since PLA2G7 is induced by ERG and is highly expressed especially in the ERG positive prostate cancers, it is a putative biomarker for this subgroup of prostate cancers." (PMID 22202492, 2011). "In 2005 the most frequent genetic alteration involving ERG was found in prostate cancer (PCa), where the 5′-untrascribed region of the prostate-specific and androgen-responsive TMPRSS2 gene is fused to ERG in approximately 50% of PCa cases." (PMID 22140532, 2011). "The TMPRSS2-ERG fusion gene is a frequent genomic rearrangement in prostate cancers that results in placing the ERG ETS-family transcription factor under the androgen-regulated expression of the TMPRSS2 gene." (PMID 22035283, 2011). "Previous reports of the SLC45A3-ELK4 e4-e2 TIC have found it to be specific to prostate cancer samples, particularly those that lack ERG expression." (PMID 21261984, 2011). "The main motivation of this study is therefore to unravel such TMPRSS2/ERG related pathways in the context of prostate cancer." (PMID 21747944, 2011). "Recently, a frequent chromosomal aberration fusing androgen regulated TMPRSS2 promoter and the ERG gene (TMPRSS2/ERG) was discovered in prostate cancer." (PMID 21747944, 2011). "This knowledge in combination with frequent expression and vital function of PLA2G7 in ERG positive prostate cancer cells provides a significant opportunity for drug repositioning." (PMID 22202492, 2011). "Several studies demonstrated that compared to PIN lesions, TMPRSS2/ERG rearrangement frequency in localized invasive prostate cancers, is doubled." (PMID 21747944, 2011). "PCSD1 xenograft tumors were characterized as PSA+, AR+, K5-, K14-, K8+, K18+, AMACR+, NKX3.1+, and TMPRSS2:ERG- human prostate cancer." (PMID 22035283, 2011). "This discovery provides novel insights into the role of TMPRSS2/ERG in prostate cancer progression and describes a new mechanism for PIM1 regulation mediated by the ERG DNA binding domain." (PMID 22140532, 2011). "The antiproliferative and pro-apoptotic effect of PLA2G7 impairment was seen in the ERG positive prostate cancer cells, indicating that ERG positive prostate cancer cells are dependent on PLA2G7 function." (PMID 22202492, 2011). "This information provides a potential link between inhibition of PSMA by androgen and ERG expression in fusion-positive prostate cancer cells." (PMID 21731703, 2011). "In order to reveal the lipidomic changes induced by PLA2G7 impairment, cellular lipidomic profiles were analyzed in ERG positive VCaP prostate cancer cells expressing PLA2G7 at high levels." (PMID 22202492, 2011). "We have recently identified phospholipase 2 group VII (PLA2G7) as a potential drug target especially in ERG oncogene positive prostate cancers." (PMID 22202492, 2011). "The discovery of ERG/ETV1 gene rearrangements and PTEN gene loss warrants investigation in a mechanism-based prognostic classification of prostate cancer (PCa)." (PMID 20104229, 2010). "Comparison of PSA, PCA3 and TMPRSS2:ERG mRNA copy levels in CTC enriched fractions from androgen-dependent prostate cancer patients." (PMID 20598135, 2010). "A preliminary investigation of TMPRSS2:ERG mRNA transcript levels in blood specimens of prostate cancer patients has been reported." (PMID 20598135, 2010). "Although differences among the top models were marginal, the best classifier of lethal prostate cancer included Gleason score and ERG rearrangement status (AUC = 0.79; 95% CI = [0.71,0.87])." (PMID 20233430, 2010). "Comparison of PSA, PCA3 and TMPRSS2:ERG mRNA copy levels in CTC enriched fractions from androgen-independent prostate cancer patients." (PMID 20598135, 2010). "Our objective is to present recent findings on the application of PCA3 and TMPRSS2:ERG in prostate cancer diagnosis and management." (PMID 24281166, 2010).
prostate carcinoma (continued). "Next, we probed the functional relationship between ERG and EZH2 and the possibility of direct regulation of EZH2 by ERG in prostate cancer cells, in which we experimentally up- and down-regulated ERG." (PMID 20479932, 2010). "TMPRSS2:ERG gene fusion mRNAs have been associated with aggressive prostate cancer morphology in tissues and a preliminary study using a combination of TMPRSS2:ERG plus PCA3 assays has shown synergistic diagnostic utility in urine specimens." (PMID 20598135, 2010). "It should be noted that the prevalence of TMPRSS2:ERG gene fusions in prostate cancer is 44-50% in serum PSA-screened cohorts and 15-36% in population-based cohorts." (PMID 20598135, 2010). "In various studies, approximately half of all prostate cancers have been observed to overexpress the ETS family gene ERG, predominantly as a consequence of different chromosomal translocations." (PMID 20860828, 2010). "Fusion genes causing ERG overexpression can be detected in some pre-neoplastic HG-PINs, but more consistently in invasive carcinomas supporting a role of ERG in promoting prostate cancer invasion and progression." (PMID 20860828, 2010). "EZH2 promoter occupancy by ERG was also demonstrated in prostate cancer clinical samples, providing in vivo evidence of this interaction." (PMID 20479932, 2010). "The association between ERG rearranged cases and the lethal phenotype suggests that ETS rearrangements describe a particularly aggressive subclass of prostate cancer." (PMID 20233430, 2010). "Furthermore, the TMPRSS2–ERG fusion may have an important prognostic and predictive value, because of which differentially regulated mRNAs (most notably ERG) in repeated experiments suggest that targeted therapy in prostate cancer could be aided by this biomarker." (PMID 20068566, 2010). "Fusion of the androgen-regulated gene, TMPRSS2, with ERG occurs in up to 60% of prostate cancers and is likely to account for the majority of ETS oncogene rearrangements in prostate cancer." (PMID 19223900, 2009). "Using this array, proof of principle was demonstrated by detection of known fusion genes (such as TCF3:PBX1, ETV6:RUNX1, and TMPRSS2:ERG) from all six positive controls consisting of leukemia cell lines and prostate cancer biopsies." (PMID 19152679, 2009). "This included two leukemia cell lines, RCH-ACV and REH, known to carry the TCF3:PBX1 and ETV6:RUNX1 fusion genes, respectively, and four prostate cancer samples positive for the TMPRSS2:ERG fusion gene." (PMID 19152679, 2009). "Around 60% of prostate cancers are reported to contain fusions of the androgen regulated gene TMPRSS2 to ERG9, 11–14 which causes high level expression of 3′-ERG gene sequences." (PMID 19638540, 2009). "The TAPG group has shown in an earlier paper that fluorescence in situ hybridisation for the detection of the TMPSS/ERG translocation also identifies aggressive prostate cancer." (PMID 19293807, 2009). "Recently, fusion of the prostate-specific androgen-regulated TMPRSS2 gene to the ETS family transcription factor gene ERG was reported as a common event in prostate cancer." (PMID 18594527, 2008). "Our panel(s) included probe sets for three members of the ets family involved in prostate cancer; ERG, ETV1, and ETV4, as well as their translocation partner, TMPRSS2." (PMID 18846227, 2008). "We included oligonucleotide probe sets for the three major members of the ets family involved in prostate cancer: ERG, ETV1, and ETV4, as well as their translocation partner TMPRSS2." (PMID 18846227, 2008). "In FBAT models, for breast cancer rs2836391 (rank 46, p = 0.0012), is in ERG, an oncogene important in the development of prostate cancer." (PMID 17903305, 2007). "The prostate-specific gene, TMPRSS2 is fused with the gene for the transcription factor ERG in a large proportion of human prostate cancers." (PMID 17971772, 2007). "The presence of TMPRSS2 fusion with ERG in prostate cancer samples was examined by RT–PCR of RNA for all cases." (PMID 17971772, 2007).